RIPK3 (receptor interacting serine/threonine kinase 3)
Diseases named in the same sentence as RIPK3 in open-access papers (continued):
Sharing a sentence is not in itself a finding about the gene and the disease.
myocardial hypertrophy (continued). "Moreover, apoptosis was significantly improved in RIPK3−/− mice with myocardial hypertrophy." (PMID 37833985, 2023). "The results showed that RIPK3 deficiency could alleviate cardiac dysfunction, myocardial injury, aggravation of necrosis, and CaMKII activation induced by TAC surgery in mice with myocardial hypertrophy." (PMID 37833985, 2023). "Therefore, we considered that inhibition of RIPK3 could correct myocardial CaMKIIδ alternative splicing disorder in mice with cardiac hypertrophy." (PMID 37833985, 2023). "Furthermore, the present study attempted to reveal whether silencing and downregulating of RIPK3 can regulate CaMKII δ alternative splicing and CaMKII activity to delay the pathogenesis of cardiac hypertrophy." (PMID 36046685, 2022). "However, the potential protective role of inhibition of RIPK3, a regulator of CaMKII, on cardiac hypertrophy remains unclear." (PMID 36046685, 2022). "Finally, the ultrastructure of mitochondria in the left ventricle of myocardial hypertrophy mice was observed by transmission electron microscopy, and mitochondrial irregularity, swelling, and cristae rupture were all ameliorated in RIPK3−/− mice compared to myocardial hypertrophy WT mice." (PMID 36046685, 2022). "RIPK3 inhibitor GSK872 can inhibit the activation of CaMKII, alleviate regulated necrosis and oxidative stress to alleviate myocardial hypertrophy." (PMID 41499472, 2026). "Overexpression of RIPK3 simultaneously up-regulated the expression of RIPK1 and the phosphorylation of MLKL in the myocardial tissues of mice with cardiac hypertrophy." (PMID 37833985, 2023). "By WGA staining, it was observed that in the cross-sectional area of mouse cardiomyocytes the IVS and LVPW of each myocardial hypertrophy mouse group were significantly increased (P < 0.05), compared with WT (AMP-AngII)+NS group given RIPK3 inhibitor GSK'872." (PMID 36046685, 2022). "HE staining revealed that the RIPK3 inhibitor GSK'872 alleviated myocardial cell distortion and disorder in myocardial hypertrophy mice." (PMID 36046685, 2022). "The results indicated that deletion of the RIPK3 gene or administration of GSK'872 could reduce CaMKII activity, alleviate oxidative stress, reduce necroptosis, and reverse myocardial injury and cardiac dysfunction caused by AngII-induced cardiac hypertrophy in mice." (PMID 36046685, 2022). "RIPK3 interacts with its downstream target, MLKL, to promote itslocalization to the cell membrane and increases the influx of intracellularcalcium, thus facilitating the progression of myocardial hypertrophy." (PMID 39484135, 2024). "The measurement and statistics of mouse heart index IVS, LVPW, HW, HMI, LVMI, and LVMI/TL also proved that depletion of RIPK3 did not affect the degree of myocardial hypertrophy induced by TAC surgery in mice." (PMID 37833985, 2023). "Wild-type (WT) and RIPK3 gene knockout (RIPK3−/−) mice were implanted subcutaneously with Alzet miniosmotic pumps (200 μL) and perfused with angiotensin II (AMP-AngII) to induce cardiac hypertrophy." (PMID 36046685, 2022). "In AngII-induced cardiac hypertrophy RIPK3−/− mice, there was no significant expression of RIPK3 protein (P > 0.05) when compared with the WT (AMP-AngII) group." (PMID 36046685, 2022). "However, in mice with myocardial hypertrophy, the lack of RIPK3 significantly increased EF and FS, indicating that the cardiac function of the mice was improved." (PMID 37833985, 2023). "Moreover, the depletion of the RIPK3 gene did not affect the expressions of the hypertrophic genes in mice with myocardial hypertrophy." (PMID 37833985, 2023). "In summary, although depletion of RIPK3 did not change the degree of myocardial hypertrophy, it could significantly improve the central dysfunction of myocardial hypertrophy, such as myocardial injury, myocardial fibrosis, and inflammation." (PMID 37833985, 2023).
Nephropathy (8 papers, 2016 to 2024). A nonspecific term referring to disease or damage of the kidneys. "This pathway is often associated with kidney disease and is defined at the molecular level by the involvement of three proteins: receptor-interacting serine/threonine protein kinase 3 (RIPK3), RIPK1, and the executioner pseudokinase mixed-lineage kinase domain-like protein (MLKL)." (PMID 38704372, 2024). "RIPK1 kinase-deficient (KD) mice, RIPK3−/− mice, and/or treatment with Nec-1 all showed nephroprotective effects in almost all forms of kidney injuries, which confirms that necroptosis plays a critical role in the development of renal diseases." (PMID 36361505, 2022). "In these conditions, RIPK3-mediated necrosis would be facilitated and contribute to the pathophysiology of Immune mediated nephropathy." (PMID 27669412, 2016). "Additionally, disruption of Smad2 also reduced RIPK1 and RIPK3, the central regulators in necroptosis in cisplatin nephropathy." (PMID 31754396, 2019). "Furthermore, we investigated the anti-inflammatory effects and inhibition of necroptosis of Cpd-42, and the results indicated that Cpd-42 reversed the mRNA expression of TNF-α and MCP-1, phosphorylation of p65 and activation of the RIPK3-MLKL signalling pathway in CaOx-induced nephropathy." (PMID 36408256, 2022). "Previous studies have described that regulated necrosis pathways are activated during FA-AKI and are associated with the upregulation of components in this cell death pathway, such as RIPK3 and MLKL, contributing to cell death and kidney damage." (PMID 37627536, 2023). "Several studies have observed the role of necroptosis (e.g., higher RIPK1, RIPK3, and MLKL expression and/or phosphorylation levels) in different forms of kidney disease." (PMID 36361505, 2022). "Since previous studies demonstrated that necrosis in females with Immune mediated nephropathy was occurring independently of PARP1, we hypothesized that RIPK3-driven pathways may instead mediate necrosis in this setting." (PMID 27669412, 2016). "Our results demonstrate that cell death triggered by autoantibodies and complement, the effector function of the autoimmune process that lead to kidney disease, is not RIPK3-dependent necroptosis." (PMID 27669412, 2016). "As expected in the pristane model, treated mice did not develop kidney disease and shown by renal histology scores; moreover both RIPK3-/- and B6 mice of both sexes developed similar levels of anti-nuclear antibodies." (PMID 27669412, 2016).
osteosarcoma (8 papers, 2012 to 2025). A usually aggressive malignant bone-forming mesenchymal neoplasm, predominantly affecting adolescents and young adults. "Shikonin inhibited lung metastases by inducing RIPK1- and RIPK3-dependent necroptosis in osteosarcoma, or regulated the production of reactive oxygen species (ROS) through RIPK3 to inhibit tumor cell proliferation and metastasis." (PMID 35814424, 2022). "Towards this end, optimization of pharmacologic therapy to effect RIPK3 demethylation may represent a novel therapeutic intervention that facilitates improved outcomes in pediatric patients with chemo resistant osteosarcoma." (PMID 40332549, 2025). "Interestingly, RIPK3 levels varied considerably in cells from the metastatic osteosarcomas: 1029LV and 493L expressed robust levels, 494L expressed less, and none was detected in lysates of cells from the metastatic tumors 98L, 147L or 148L." (PMID 27129149, 2016). "For example, the anticancer drug shikonin exerts an antitumor effect on osteosarcoma by triggering RIPK1- and RIPK3-dependent necroptosis." (PMID 40573272, 2025). "Mechanically, TNFRSF21 upregulated the phosphorylation levels of RIPK1, RIPK3 and MLKL to promote necroptosis in osteosarcoma." (PMID 38184626, 2024). "Shikonin significantly reduces osteosarcoma metastasis by inducing receptor-interacting protein 1 (RIPK1)- and RIPK3-dependent necroptosis." (PMID 37061535, 2023). "To test the hypothesis that TNFRSF21 promoted necroptosis in osteosarcoma, we examined the phosphorylation levels of RIPK1, RIPK3 and MLKL." (PMID 38184626, 2024). "RIPK3 levels varied considerably between tumors and RIPK3 was not required for IAP antagonism to sensitize osteosarcoma cells to TNFα." (PMID 27129149, 2016). "The responsive cells could be protected by pre-treatment with necrostatin, and cells from some of the sensitive osteosarcomas expressed little or no RIPK3." (PMID 27129149, 2016).
pancreatic ductal adenocarcinoma (8 papers, 2022 to 2025). An infiltrating adenocarcinoma that arises from the epithelial cells of the pancreas. "An enhanced antitumor immune response was associated with this phenomenon, as evidenced by increased lymphocyte infiltration and decreased immunosuppressive medullary cell infiltration in RIPK3-deficient pancreatic ductal carcinoma." (PMID 38546403, 2024). "In particular, the proteomics analysis derived from shows higher levels of RIPK1 compared to RIPK3 within the Pancreatic Ductal Adenocarcinoma in both normal and tumor tissues, which is also in line with our data (Fig. EV4A)." (PMID 40240880, 2025). "It was found that in vivo experiments involving the deletion of RIPK3 or inhibition of RIPK1 resulted in a delay in the progression of pancreatic ductal carcinoma in mice." (PMID 38546403, 2024). "Previous research results show that in pancreatic ductal adenocarcinoma, if RIPK3 is knocked out, the diseased cells will necrosis." (PMID 37878133, 2023). "Analogously, in pancreatic ductal adenocarcinoma, RIPK3 expression is significantly upregulated compared with that in normal tissues, whereas RIPK3 deletion mitigates the expression of the chemokine CXCL1 in vivo and in vitro." (PMID 36482419, 2022). "Moreover, a previous study demonstrated that RIPK3 blockade protects against pancreatic ductal adenocarcinoma progression via promoting infiltration of T cells and B cells." (PMID 36505813, 2022). "In pancreatic ductal carcinoma, there have been observations of elevated expressions of RIPK1 and RIPK3." (PMID 38546403, 2024). "RIPK3 was found highly expressed in pancreatic ductal adenocarcinoma (PDA), deletion of RIPK3 protects against oncogenic progression of PDA, which partially depends on necroptosis-induced expression of CXCL1 that promotes macrophage-induced adaptive immune suppression." (PMID 39872161, 2022).
acute pancreatitis (7 papers, 2017 to 2023). An acute inflammatory process that leads to necrosis of the pancreatic parenchyma. "employed the cerulein-induced acute pancreatitis model, in RIPK3 knockout mice as well as in mice carrying a mutation in the kinase domain of RIPK3, rendering it catalytically inactive." (PMID 37409125, 2023). "In animal models of acute pancreatitis, ischemic injury, and neurodegeneration that are related to RIPK1/RIPK3 deficiency or MLKL knockout, it has been suggested that necroptosis may be a key element in triggering inflammation." (PMID 35276962, 2022). "The authors used knockouts for both RIPK3 and MLKL and showed that RIPK3 deficiency resulted in a more severe pancreatic inflammation and disease, and MLKL deficiency rendered mice even more susceptible to tissue damage caused in the cerulein-induced acute pancreatitis model." (PMID 37409125, 2023). "Additionally, Necroptosis that is dependent upon RIPK3 and MLKL was also shown to worsen tissue inflammation and injury in an acute pancreatitis mouse model." (PMID 29123466, 2017).
cardiac ischemia (7 papers, 2015 to 2025). "RIPK3-dependent calcium/calmodulin-dependent kinase (CaMKII) activation plays a key role in necroptosis in cardiac ischemia-reperfusion injury models." (PMID 36756299, 2023). "Sevoflurane postconditioning-induced enhancement of O-GlcNAcylation of RIPK3 (necrosis regulatory protein) inhibits myocardial ischemia-reperfusion injury-mediated necrosis through inhibition of RIPK3/MLKL (a key mediator of necrosis) complex formation." (PMID 37251080, 2023). "Ripk3-mediated Necroptosis and mitochondria-mediated apoptosis are the main types of cell death in myocardial ischemia." (PMID 35187131, 2022).
Cerebral ischemia (7 papers, 2018 to 2025). Restriction of arterial blood supply to the brain associated with insufficient oxygenation to support the metabolic requirements of the tissue. "Dabrafenib, a B-raf inhibitor currently used in cancer therapies that was subsequently found to be a strong inhibitor of RIPK3 at moderate doses has also been found to confer a neuroprotective benefit in cerebral ischemia." (PMID 33142926, 2020). "Oxygen-glucose deprivation (OGD), an in vitro model of cerebral ischemia, can also induce the death receptor (DR)-dependent component of necroptotic cell death in cultured neurons, concomitant with the increase in RIPK3/RIPK1 mRNA and protein levels." (PMID 29686306, 2018). "In contrast with wild‐type mice, RIPK1 kinase‐dead mice, RIPK3 deficient mice, and MLKL deficient mice showed reduced levels of cell necrosis and neuroinflammation after cerebral ischemia, which is highly consistent with the apoptotic pathway of necrotic cells." (PMID 39657719, 2024). "Our data suggest that (i) p-RIPK1 (Ser166) participated in RIPK3/MLKL-dependent neuronal necroptosis after cerebral ischemia; (ii) immunostaining with a specific antibody against p-RIPK1 (Ser166) could be used as a morphological biomarker for necroptosis." (PMID 31440386, 2019). "The expression of necroptosis kinases, including MLKL/p-MLKL, RIPK3/p-RIPK3, and RIPK1/p-RIPK1, was significantly increased in the brain tissue of an OGD-induced neuronal injury model and the brain tissue of cerebral ischemia animal models." (PMID 40636901, 2025). "We found that cerebral ischemia stimulated phosphorylation of RIPK1 at the Ser166 residue and increased RIPK3 and MLKL expression levels in the brain." (PMID 31440386, 2019).
cholangiocarcinoma (7 papers, 2017 to 2024). A carcinoma that arises from the intrahepatic biliary tree (intrahepatic cholangiocarcinoma) or from the junction, or adjacent to the junction, of the right and left hepatic ducts (hilar cholangiocarcinoma). "More interestingly, matrine was able to upregulate the expression of RIPK3 in Mz-ChA-1 cells, making it possible to treat cholangiocarcinoma with a low expression of RIPK3." (PMID 34680470, 2021). "Quercetin and kaempferol, which are natural flavonoids, when used in combination with Smac mimetics, induce the proteasomal degradation of cellular inhibitor of apoptosis proteins one and 2 (cIAP1/2) and synergistically kill cholangiocarcinoma cells through RIPK1/RIPK3/MLKL-mediated necroptosis." (PMID 39584140, 2024). "For instance, researchers have found that gemcitabine could induce RIPK1/RIPK3/MLKL-dependent necroptosis in cholangiocarcinoma cells." (PMID 35756487, 2022). "Matrine, an alkaloid derived from Sophora flavescens, upregulates RIPK3 expression and promotes MLKL translocation from the cytoplasm to the cell membrane, ultimately inducing necroptosis in cholangiocarcinoma." (PMID 39584140, 2024).
gastric cancer (7 papers, 2021 to 2025). A primary or metastatic malignant neoplasm involving the stomach. "Prunetrin (prunetin 4-O-glucoside), a glycosyloxy isoflavone derived from Prunus species, interacts with receptor-interacting serine/threonine-protein kinase 3 (RIPK3) and triggers some cells death stages in gastric cancer." (PMID 40149274, 2025). "Gentiopicroside enhanced p-RIPK3/RIPK3 protein levels and p-MLKL/MLKL protein levels, suggesting the activation of necroptosis in gastric cancer SGC7901 cells." (PMID 39570876, 2024). "Correlation between higher RIPK3 mRNA expression and OS was not statistically significant in gastric cancer patients as whole in this database; however, it was significant in later-stage (stage 3) gastric cancers." (PMID 34419074, 2021).
glioblastoma (7 papers, 2014 to 2025). The most malignant astrocytic tumor (WHO grade IV). "The RIPK1-dependent necroptosis inhibitors necrostatin-1 (Nec-1) and Nec-1s as well as siRNA-mediated silencing of RIPK3 inhibited edelfosine-induced necroptosis, resulting in increased caspase-dependent apoptosis in edelfosine-treated glioblastoma U118 cells." (PMID 25593994, 2014).
intestinal tumor (7 papers, 2020 to 2025). "In this study, we found that loss of RIPK3 promoted the initiation and progression of spontaneous intestinal tumors." (PMID 33996591, 2021). "Jayakumar demonstrated that the necroptosis gene RIPK3 can induce inflammation through intermediate MDSCs to promote intestinal tumor growth." (PMID 35719998, 2022). "In COAD, RIPK3-mediated inflammation can promote intestinal tumors by inducing an immune-suppressive tumor microenvironment, and RIPK1 has been shown to interact with mitochondrial Ca2+ uniporter to promote colorectal oncogenesis." (PMID 36505813, 2022). "To evaluate the status of STAT3 in intestinal epithelial cells and tumors from Apcmin/+Ripk3-/- mice, we analyzed protein expression in intestinal tumors and colon crypt cells." (PMID 33996591, 2021). "Thus, cooperation with increased proliferation and decreased apoptosis contributes to accelerated intestinal tumors in Apcmin/+Ripk3-/- mice." (PMID 33996591, 2021). "It is hypothesized that the promotion of intestinal tumours by Ripk3/I‐MDSCs was mediated by TLR4/GM‐CSF signalling." (PMID 31650683, 2020). "For instance, RIP kinase 3 (RIPK3) and RIPK1 have been demonstrated to have anti-tumorigenic capacity in CRC, although RIPK3-mediated inflammation can induce an immune-suppressive tumor microenvironment (TME), thereby facilitating intestinal tumor progression." (PMID 40959081, 2025). "Thus, our results reveal that RIPK3 is a tumor suppressor in spontaneous intestinal tumorigenesis, and implicate targeting the IL-6/STAT3 signaling axis as a potential therapeutic strategy for intestinal tumor patients with reduced RIPK3." (PMID 33996591, 2021).
non-alcoholic steatohepatitis (7 papers, 2015 to 2024). "In addition, RIPK3 is overexpressed in patients with nonalcoholic steatohepatitis (NASH) and is associated with liver inflammation and fibrosis." (PMID 38684668, 2024). "In non-alcoholic steatohepatitis (NASH) mice, hepatic ATF3 deficiency suppresses RIPK3 expression and hepatocellular death." (PMID 36690638, 2023). "Furthermore, the induction of RIPK3 in humans has been shown in non-alcoholic steatohepatitis." (PMID 33791319, 2021). "Activation of RIPK3 promoted inflammatory injury in non-alcoholic steatohepatitis, whereas disruption of RIPK3 dampened inflammation and non-alcoholic steatohepatitis progression." (PMID 37841640, 2023).